INS (insulin)
Diseases named in the same sentence as INS in open-access papers (continued):
Sharing a sentence is not in itself a finding about the gene and the disease.
Hyperglycemia (continued). "The suppression of insulin secretion by afferent VNS is consistent with the sustained hyperglycemia observed with combined afferent and efferent VNS and with selective afferent VNS." (PMID 26884478, 2016). "When glucose is infused in rats in late gestation, this provokes hyperglycemia-induced disorders in insulin secretion in offspring." (PMID 27314367, 2016). "In vivo, Ad36 or E4orf1 improve high-fat diet induced hyperglycemia and up-regulate the distal insulin signaling in muscle, and adipose tissue for glucose clearance." (PMID 27537838, 2016). "Animals receiving oxidised palm oil + sucrose were also characterized by hyperglycemia, glucose intolerance and insulin insensibility." (PMID 26841874, 2016). "It reduces hyperglycemia by suppressing hepatic glucose output so it reduces hepatic gluconeogenesis and it is intensifying insulin sensitivity therefore enhancing peripheral glucose uptake." (PMID 27597988, 2016). "In parallel, hyperglycemia potentiates oxidative stress via activation of the ceramide and diacylglycerol pathways and other intermediaries, which also hinder insulin signaling." (PMID 27579182, 2016). "The management of hyperglycemia in patients with diabetic kidney disease is even more difficult, requiring adjustment of antidiabetic agents and insulin doses." (PMID 26872083, 2016). "Our aim was to examine the effects of transient post-prandial hyperglycemia, which occurs in both healthy individuals and, more severely, in the insulin resistant." (PMID 26752052, 2016). "- risks of insulin administration itself: hypo- or hyperglycemia; difficulties in learning to distinguish between the types of insulin and their effects, or in learning to adjust doses; lipodystrophy at the injection site." (PMID 27928433, 2016). "In conclusion, EPA corrected not only postprandial hypertriglyceridemia but also postprandial hyperglycemia and insulin secretion ability." (PMID 27565734, 2016). "An improvement in glucose and insulin tolerance, insulin secretion, and reduced hyperglycaemia were observed in diabetic rats and dogs." (PMID 27879673, 2016). "Insulin levels were positively correlated with prepregnancy BMI (r = 0.38, p = 0.0009), gestational BMI (r = 0.24, p = 0.0466) and hyperglycemia (r = 0.26, p = 0.0252)." (PMID 27651836, 2016). "DM is a complex metabolic disorder characterized by chronic hyperglycemia, due to reduced insulin secretion and often in combination with insulin resistance (IR)." (PMID 27406855, 2016). "We reported that impaired early-phase insulin secretion plays the more important role in deterioration from normal glucose tolerance (NGT) via isolated IGT to isolated postchallenge hyperglycemia (IPH) in Japanese." (PMID 26788515, 2016). "Most patients required basal-bolus insulin to control hyperglycemia, although specific regimens differed according to DM history." (PMID 28031946, 2016). "At initial stages of hyperglycaemia, the liver facilitates glucose uptake while at later stages, the liver develop insulin resistance and facilitates glucose output." (PMID 26790104, 2016). "T2DM is characterized by hyperglycemia resulting in production of increased hepatic glucose, impairment of insulin production by pancreatic β-cells, and insulin resistance." (PMID 27547756, 2016). "Hyperglycemia should be treated promptly with insulin injection by syringe and changing the infusion set and if necessary, presentation to triage for hydration and intravenous insulin and correction of electrolyte abnormalities." (PMID 27337958, 2016). "In contrast, mice exposed to chronic hyperglycaemia exhibited marked changes in insulin content and islet structure: these mice either required substantially more sulfonylurea to achieve normoglycaemia or sulfonylurea therapy was ineffective." (PMID 27033559, 2016).
Hyperglycemia (continued). "It has been demonstrated that PA is related to the increased insulin sensitivity in the liver and muscle, and improved hyperglycemia and hypertriglyceridemia through increasing insulin sensitivity and altering liver lipid metabolism in diabetic rats." (PMID 27964715, 2016). "In this instance, dietary supplementation with curcumin prevented hyperglycemia, increased insulin production and lean body mass, and prolonged lifespan." (PMID 27110686, 2016). "IPGTTs showed that the onset of hyperglycaemia was preceded by reduced glucose tolerance and significant delay in acute insulin secretion in young adult Aldh1b1tm1lacZ null mice." (PMID 26518685, 2016). "The inability of insulin to suppress hepatic glucose production increases fasting glucose, which stimulates insulin secretion leading to hyperglycemia and hyperinsulinemia." (PMID 27128911, 2016). "Further insulin administration and hyperglycemia facilitate further glycogen synthesis, which creates congested hepatocytes resulting in storage overload." (PMID 27699071, 2016). "As sugars easily cross the placenta, the fetal pancreas responds to hyperglycemia by increasing insulin production." (PMID 27476441, 2016). "Our studies reveal that administration of proteasome inhibitors to these mice corrects their hyperglycemia, and appears to do so by increasing insulin sensitivity and by preserving β-cell function." (PMID 27110686, 2016). "Six months of EPA treatment improved not only fasting atherogenic lipid derangements and postprandial hypertriglyceridemia, but also postprandial hyperglycemia and insulin secretion ability." (PMID 27565734, 2016). "Somatostatin from the δ-cells is a potent inhibitor of both insulin and glucagon release and was early proposed as a paracrine regulator of glucagon release mediating the inhibitory effect of hyperglycaemia." (PMID 27044660, 2016). "Other reasons included dropout from treatment, addition of other drugs due to hyperglycemia, or insulin therapy under hospitalization." (PMID 26925169, 2016). "A single injection of these compounds raised circulating insulin levels within 24 h and substantially reduced hyperglycemia in these mice for nearly 48 h." (PMID 27110686, 2016). "Suppression of hepatic gluconeogenesis by insulin is an important process to inhibit hyperglycaemia." (PMID 27412556, 2016). "Therapeutic management of DKA is yet to be optimised but includes adequate fluid replacement and insulin infusion to correct electrolyte imbalance and hyperglycaemia, respectively." (PMID 27073901, 2016). "Overexpression of FoxO1 has been reported to act against hyperglycemia-induced oxidative stress, and prevent β cell replication in an insulin-resistant state through decreasing glucose utilization and insulin secretion, a process known as “metabolic diapause”." (PMID 27861641, 2016). "In all of these models it is difficult to separate the relative contribution of intrinsic defects in cardiomyocyte insulin signaling from the conditions generated by the altered systemic metabolism, such as hyperglycaemia and hyperlipidaemia." (PMID 27014078, 2016). "As early as 3 weeks after Dicer deletion, the null mice presented with marked hyperglycemia and glucose intolerance, mainly due to a severe reduction in β-cell insulin gene expression." (PMID 28123396, 2016). "Insulin-mimetic attributes of decavanadate were challenged in two models with different metabolic disturbances, but with hyperglycemia in common." (PMID 27119007, 2016). "The patient had persistent hyperglycemia, requiring insulin in high doses, followed by hypoglycaemia at intervals." (PMID 26761945, 2016). "A study by Ceriello and colleagues also demonstrated the beneficial effects of targeting hyperglycemia and oxidative stress (OxS) and endothelial dysfunction simultaneously using insulin and an antioxidant (vitamin C)." (PMID 27793203, 2016).
Hyperglycemia (continued). "In some cases, pancreatic islet cell transplantation can reverse hyperglycemia in T1D and negate the use of insulin therapy." (PMID 27755557, 2016). "Insulin concentrations correlated positively with prepregnancy BMI (r = 0.38), gestational BMI (r = 0.24) and maternal hyperglycemia (r = 0.26)." (PMID 27651836, 2016). "Most studies measured: early mortality, ventilator duration, infection rates, hyperglycaemia and insulin requirement, low cardiac output prevalence, fluid balance and intensive care unit (ICU) length of stay." (PMID 27489622, 2016). "IGF-II and insulin were both less effective in high compared to low glucose conditions; thus, hyperglycemia induced both relative insulin- and IGF-II-resistance in terms of proliferation." (PMID 27733843, 2016). "Kaempferol extracted from Bauhinia forficata leaves reduced hyperglycemia and enhanced glucose uptake in the rat soleus muscle similarly to the action of insulin." (PMID 27092490, 2016). "Hyperglycemia is an expected side effect of PI3K/AKT/mTOR pathway inhibition given the role of the pathway in regulating insulin signaling and glucose homeostasis." (PMID 26931343, 2016). "In a diabetic state, the liver becomes resistant to the actions of insulin and there is an increase in hepatic glucose production, which is a major contributor to hyperglycemia." (PMID 26927057, 2016). "High leptin levels are associated with reduced insulin secretion, increased gluconeogenesis and reduced glucose uptake, leading to hyperglycemia and ultimately contributing to increased insulin resistance." (PMID 27973438, 2016). "Affected individuals from this family had histories of hyperglycemia (plasma glucose > 6 mmol/L, fasting) with normal fasting insulin levels." (PMID 26981542, 2016). "At hyperglycaemia GIP indeed stimulates insulin release, but in the presence of euglycaemia or hypoglycaemia GIP stimulates glucagon secretion." (PMID 26859145, 2016). "To investigate the mechanism by which curcumin prevents hyperglycemia in Leprdb/db Ks mice, we measured fasting circulating insulin levels in lean Ks and obese Leprdb/db Ks mice on control and curcumin-supplemented diets." (PMID 27110686, 2016). "Mice challenged with HFD initially show β-cell compensation, with relative hyperinsulinemia and normoglycemia, but this is invariably followed by β-cell failure, impaired insulin secretion and hyperglycemia." (PMID 27053133, 2016). "Mice with a continuous HFD feeding showed significant hyperglycemia and hyperinsulinemia, while an alternating diet suppressed insulin levels and pancreatic insulin gene expression." (PMID 27189661, 2016). "In contrast, in the STZ mice, Inpp5f is upregulated by hyperglycemia and hyperlipidemia and decreased by low insulin signal." (PMID 26908121, 2016). "Although only one blood glucose value of <2.8 mmol/L had been recorded, the owner-physician interpreted the relative hyperglycemia during this period to represent rebound hyperglycaemia, and continued to taper the dose of insulin." (PMID 27766967, 2016). "The polar extract modulated glucose metabolism by correcting hyperglycemia, while the lipophilic extract lowered insulin secretion." (PMID 28025494, 2016). "Maternal Antecedents of Adiposity and Studying the Transgenerational role of Hyperglycemia and Insulin (MAASTHI) is a cohort study in the public health facilities in Bangalore, India." (PMID 27741952, 2016). "Several findings are interesting for further exploration: treatment with intravenous insulin is a possible surrogate marker for severe hyperglycemia in our cohort." (PMID 27430328, 2016). "It has been proven that a large number of cells (10 million/mouse, equivalent to 1000 functional islets) in a mouse-to-mouse transplantation is needed to correct hyperglycemia in vivo when either the differentiation efficiency or the insulin content was low." (PMID 26756576, 2016).
Hyperglycemia (continued). "These mice developed hyperglycemia in adulthood due to impairment of glucose-stimulated insulin secretion." (PMID 26901059, 2016). "Meal announcements are often part of control algorithms, because this enables the delivery of an insulin bolus to minimize postprandial hyperglycemia." (PMID 27352278, 2016). "The insulin levels were analyzed in mouse plasma during the peak of hyperglycemia (1 h after envenoming)." (PMID 27660634, 2016). "Impaired release of glucagon-like peptide-1 (GLP-1) has been reported to be at least partly involved in impairment of early-phase insulin secretion after food intake and postprandial hyperglycemia and hyperlipidemia." (PMID 26734075, 2016). "It is well known that corticosteroid induces hyperglycemia mainly by reducing insulin-mediated glucose uptake." (PMID 26885529, 2016). "GLI is one of the sulphonylureas classes and it reduces the hyperglycemia by enhancing insulin secretion, while MET is one of the biguanide classes and acts to improve insulin sensitivity and suppress hepatic glucose output." (PMID 27579151, 2016). "These mice developed mild to moderate hyperglycemia, post- glucose load hyperglycemia, fasting hyperinsulinemia, and a diminished insulin response after 12 weeks feeding." (PMID 26916435, 2016). "We also found improved insulin sensitivity after chronic MP‐10 treatment further supporting the use of PDE10A inhibitors for the management of hyperglycemia." (PMID 27247380, 2016). "In line with our expectations, we received severe hyperglycaemia with simultaneous reduction of fasting plasma insulin levels (below the limit of detection) as early as 1 week after STZ injection." (PMID 27478848, 2016). "In summary, mice Mig-6 ablation in the liver result in multiple metabolic phenotypes such as fatty liver, fasting hyperglycemia, and hypercholesterolemia but in lower bodyweight and improved insulin sensitivity." (PMID 28053990, 2016). "Substantial evidence suggests that liver inflammation, which impairs hepatic insulin signaling, increases hepatic gluconeogenesis, leading to fasting hyperglycemia in T2D." (PMID 28029143, 2016). "Bilberries are one of the richest sources of anthocyanins and bilberry extract (BBE) improved hyperglycemia and insulin sensitivity in diabetic mice by targeting AMPK, GLUT4, and metabolic enzymes." (PMID 27092490, 2016). "hESCs differentiated using the Pagliuca protocol were found to secrete human insulin in response to a glucose challenge after transplantation in a manner that prevented hyperglycemia in the Akita mouse." (PMID 28702240, 2016). "SZT treatment in wild type mice has been shown to induce hyperglycaemia, but with a modest reduction in insulin production." (PMID 26914991, 2016). "Sham-operated mice died due to hyperglycemia 3 d after the withdrawal of insulin treatment, whereas ECC-transplanted mice survived more than 40 d." (PMID 27731367, 2016). "This correlated with a significant decrease in plasma insulin levels and concomitant exacerbation of hyperglycemia, despite the increased insulin sensitivity in rapa-treated TH mice." (PMID 27922820, 2016). "Transgenic mice expressing the very same cDNAs under an insulin promoter revealed that SNP rs3743123 expression consistently lead to a post-natal reduction of islet Cx36 levels and β-cell survival, resulting in hyperglycemia in selected lines." (PMID 26959991, 2016). "That is, the first peak after the SQ Lispro insulin injection nearly returned to its baseline value, just avoiding “rebound hyperglycemia”; note, this phenomenon occurred at the higher insulin doses." (PMID 26819233, 2016). "In this situation, pancreatic beta cells have to produce more insulin to overcome this insensitivity, resulting in a state of hyperglycemia and hyperinsulinemia." (PMID 26819084, 2016). "Insulin secretion is insufficient to compensate for the insulin resistance and this leads to hyperglycemia, which can be detected through routine glucose screening during pregnancy." (PMID 26975349, 2016).
Hyperglycemia (continued). "We found that treating hyperglycemia by insulin ameliorates myocardial morphological abnormalities and partially inhibits myocardial cell death." (PMID 26925289, 2016). "PI3Kɑ is involved in the signaling of insulin and, therefore, hyperglycemia is an expected on-target effect of PI3Kɑ inhibitors." (PMID 27816049, 2016). "In another study, monkey iPSC-derived β cells transplanted into a diabetic mouse model led to the production of functional insulin-secreting pancreatic β cells and hyperglycemia recovery." (PMID 26907255, 2016). "In the present experiments in high-dose STZ-treated rats, 1 insulin-releasing implant per animal was able to adjust glucose to a moderate prandial hyperglycemia (around 15 mM) over the daytime, while 2 implants reduced glucose to normoglycemia in these rats." (PMID 27253523, 2016). "After discharge, although glulisine and glargine were continued, his glycemic control worsened, with fasting and postprandial hyperglycemia levels of approximately 200 and 300 mg/dL, respectively, and high serum insulin levels persisted." (PMID 27456688, 2016). "Under fed, but not under fasted conditions, 32-week-old C2αD1268A/WT males displayed hyperglycaemia and hyperinsulinaemia, with reduced glucose clearance, despite an observed elevated insulin secretion during the glucose tolerance test (GTT)." (PMID 27138914, 2016). "Maternal hyperglycemia increases fetal insulin levels and stimulates growth, leading to higher birth weights among children born to mothers with GDM." (PMID 27825389, 2016). "In diabetic humans hyperglycemia is thought to cause mitochondrial dysfunction and fragmentation, thereby linking hyperglycemia, mitochondrial dysfunction, and temporary insulin resistance characteristics in cardiomyocytes before obvious pathology." (PMID 27547764, 2016). "Hyperglycemia indirectly influences cancer cells through upregulation of insulin/IGF-1 and inflammatory cytokines in circulation." (PMID 26443426, 2015). "Previously we showed that rats have increased body weight, slight hyperglycemia, hyperinsulinemia, glucose intolerance and a diminished insulin response to a glucose load after a 4-week fcHFHS diet." (PMID 26617484, 2015). "After this period we have observed significant hyperglycemia and concomitant high fasting plasma insulin level." (PMID 26380311, 2015). "The benefits that insulin offer are greater flexibility and predictability, rapid ability to target post-prandial hyperglycaemia, dose modification related to patient oral intake and unlimited dosing." (PMID 26550039, 2015). "They observed that diabetic mice treated with baicalein displayed significantly improved hyperglycemia, glucose tolerance, and insulin levels." (PMID 26705405, 2015). "Transplantation of insulin producing beta cells, or islets of Langerhans, can reverse hyperglycemia, and has become an alternative to insulin replacement therapy for selected patients with type 1 diabetes." (PMID 25793295, 2015). "We found that the alteration of Mio and additional proof-of-concept candidates, such as glycolysis genes, MODY homologues, insulin (Dilp) and glucagon (Akh), all produced hyperglycaemia in a manner predicted from mammalian studies." (PMID 25994086, 2015). "Similar to the C57BL/6J mice, the C3H/HeJ strain on the HF diet exhibited delayed-onset of hyperglycemia, while their plasma insulin was increased at 12, 20, and 24 wk." (PMID 26146567, 2015). "Along with lifestyle management (such as diet and adequate physical activity), treatment with oral anti-diabetic agents and/ or insulin is recommended to control hyperglycaemia." (PMID 25710465, 2015). "The condition is aggravated even after continuous insulin infusion, resulting in vomiting, and leading to significant acidosis, ketonuria, and hyperglycaemia." (PMID 26273667, 2015).